HDAC6 (histone deacetylase 6)
Diseases named in the same sentence as HDAC6 in open-access papers (continued):
Sharing a sentence is not in itself a finding about the gene and the disease.
cognitive decline (10 papers, 2013 to 2025). "For instance, studies have demonstrated that an increase in HDAC6 can suppress tau accumulation, while its deficiency has been shown to accelerate tau pathology and cognitive decline and contribute to learning deficits." (PMID 38918466, 2024). "In particular, DMP cg24616736, which was associated with HDAC6, showed the strongest correlation with progression time and the speed of cognitive decline in the LMCI patients." (PMID 38298218, 2024). "Further, HDAC6 inhibition has been shown to attenuate tau pathology, a mechanism closely linked to cognitive decline in neurodegenerative diseases." (PMID 30270813, 2018). "In summary, reducing HDAC6 levels has been shown to improve cognitive function and synaptic dysfunction in AD models, making HDAC6 inhibition a promising therapeutic strategy for treating cognitive decline in AD." (PMID 40940748, 2025). "In vivo, in a mouse model for AD with lower HDAC6 expression, required learning and memory and α-tubulin acetylation, the inhibition of HDAC6 seems to ameliorate cognitive decline." (PMID 36358670, 2022). "In this respect, data showing that pharmacological or genetic disruption of HDAC6 is protective against pathological tau-induced microtubule abnormality and cognitive decline are of great interest." (PMID 30270813, 2018). "Both LMCI and AD exhibit symptoms of cognitive decline; therefore, targeted inhibition or degradation of HDAC6 as a therapeutic approach for AD could potentially have preventive effects on the occurrence of LMCI." (PMID 38298218, 2024). "Thus, our study suggests that targeting HDAC6 could be a suitable strategy to ameliorate cognitive decline observed in AD." (PMID 23184605, 2013). "Tau transgenic mice lacking HDAC6 show reduced survival characterized by accelerated tau pathology and cognitive decline." (PMID 33139698, 2020).
HIV-1 infection (10 papers, 2015 to 2024). The type species of lentivirus and the etiologic agent of acquired immunodeficiency syndrome (AIDS). "Taken together, our results indicate that TDP-43 shapes cell permissivity to HIV-1 infection, affecting viral Env fusion and infection capacities by altering the HDAC6 levels and associated tubulin-deacetylase anti-HIV-1 activity." (PMID 35682862, 2022). "Hence, TDP-43 shapes cell permissivity to HIV-1 infection, affecting viral Env fusion and infection capacities by altering HDAC6 levels and associated tubulin-deacetylase anti-HIV-1 activity." (PMID 37685911, 2023). "In fact, we reported this NLS-TDP-43 effect on HDAC6 and its MT substrate in previous studies of HIV-1 infection." (PMID 37108826, 2023). "Regarding this, a recent study reported the functional implication of TDP-43 in determining cell permissivity to HIV-1 infection by modulating the level of expression of HDAC6 mRNA and enzyme, and therefore the acetylation level of MTs." (PMID 37685911, 2023). "Altogether, these data and the present study prompt the suggestion that TDP-43 and the TDP-43/HDAC6 axis are key to control HIV-1 infection." (PMID 37108826, 2023). "The TDP-43-mediated increase in the level of the HDAC6 enzyme and the subsequent diminution of the levels of acetylated α-tubulin in MTs promote a cellular environment that limits early HIV-1 infection, as previously reported." (PMID 35682862, 2022). "We observed that overexpression of wt-TDP-43 increased both mRNA and protein levels of HDAC6, resulting in impaired HIV-1 infection independently of the viral envelope glycoprotein complex (Env) tropism." (PMID 35682862, 2022). "Altogether, these results indicate that the efficiency of HIV-1 infection and Env-mediated cell fusion is inversely related to HDAC6 activity which is under the control of TDP-43." (PMID 35682862, 2022). "We observed that Δnef-virions lose their infection capacity when viral particles are produced in the presence of over-expressed HDAC6 (HIV-1 infection capacity/HDAC6 histogram)." (PMID 31736889, 2019). "Despite its ability to target HDAC6, stabilizing Pr55Gag, virions obtained with the Nef-G2A mutant are poorly infectious (HIV-1 infection capacity/Nef-G2A histogram)." (PMID 31736889, 2019). "Considering the anti-HIV-1 and pro-aggresome/autophagic functions of HDAC6, it is conceivable that HDAC6 regulates HIV-1 infection by the interplay of A3G and Vif proteins, and the Vif-triggered ubiquitination and subsequent proteasome degradation of A3G." (PMID 26105074, 2015). "Notably, the antiviral control exerted by HDAC6 renders the regulation of the expression of this tubulin-deacetylase a key goal to protect against HIV-1 infection." (PMID 37685911, 2023). "Therefore, the ability of HIV-1 Envs to overcome the HDAC6 barrier (i.e., the TDP-43/HDAC6 axis) and subsequently stabilize cortical MTs conditions the efficiency of the early steps of the HIV-1 infection cycle." (PMID 37108826, 2023). "To ascertain the effect of TDP-43 on HIV-1 viral production and virion infection capacity, we first studied the expression and effect of TDP-43 on HDAC6 in a well-accepted cell model for studying the HIV-1 infection cycle, such as viral particle production, as previously reported." (PMID 37108826, 2023). "The TDP-43/HDAC6 axis therefore regulates cell permissivity to HIV-1 infection." (PMID 35682862, 2022). "Therefore, TDP-43 appears to regulate cell permissivity to HIV-1 infection by conditioning viral Env-mediated fusion and infection capacities by modulating the level of expression of the antiviral HDAC6 tubulin-deacetylase enzyme." (PMID 35682862, 2022). "Therefore, the degree of permissivity to HIV-1 infection of these CD4+ T cells appears to be dependent on the level of TDP-43 which conditions the expression level of the antiviral HDAC6 enzyme and MT acetylation in α-tubulin." (PMID 35682862, 2022). "It is important to note that HDAC6 is key to regulating HIV-1 infection." (PMID 35682862, 2022).
HIV-1 infection (continued). "Interestingly, we observed that virions produced with the Nef-EA mutant, which is able to target HDAC6, present a weak infection capacity (HIV-1 infection capacity/Nef-EA histogram)." (PMID 31736889, 2019). "Indeed, this correlates well to the HDAC6-mediated Vif autophagy degradation that negatively affects HIV-1 infection, as reported." (PMID 31736889, 2019). "We propose HDAC6 as a new natural factor that restricts HIV-1 infection." (PMID 26105074, 2015). "Indeed, HIV-1 infection was impaired when viral particles were produced in HEK 293T cells overexpressing wt-HDAC6, where Vif is degraded and A3G subsequently protected." (PMID 26105074, 2015). "Altogether, these data indicate that HDAC6 is a key restriction factor that enhances its expression levels or activity (i.e., antiviral MTs deacetylation and autophagy) and could be a good strategy to explore against HIV-1 infection." (PMID 37108826, 2023). "Therefore, TDP-43 and the TDP-43/HDAC6 axis could be considered new targets for developing anti-HIV-1 strategies to control HIV-1 infection and replication, as well as against other types of viruses." (PMID 37108826, 2023). "Therefore, it is plausible that the TDP-43 action on HDAC6 could also control HIV-1 infection and replication by modulating the HDAC6-mediated autophagy anti-HIV-1 functions." (PMID 35682862, 2022). "Our results indicate that the TDP-43/HDAC6 axis could be crucial for regulating HIV-1 infection." (PMID 35682862, 2022). "Although it was observed that HDAC6 mRNA is targeted by TDP-43, thereby affecting HDAC6-mediated anti-HIV-1 activity, this might not be the only mRNA associated with proteins that may affect HIV-1 infection targeted by TDP-43." (PMID 35682862, 2022). "Therefore, the interplay between Nef and HDAC6 may be important to determine the course of HIV-1 infection and pathogenesis in infected individuals, and may contribute to the development of new strategies against HIV." (PMID 33995324, 2021). "Similar results are obtained in infection experiments with virions obtained with the Nef-LLAA mutant (HIV-1 infection capacity/Nef-LLAA histogram), which cannot target HDAC6." (PMID 31736889, 2019). "In this context, anti-viral HDAC6 action is not promoted, as previously reported to restrict HIV-1 infection." (PMID 37108826, 2023). "Decreasing acetylation of α-tubulin by HDAC6 overexpression markedly prevents HIV-1 envelope-dependent cell fusion and infection, whilst knockdown of HDAC6 expression or its inhibition enhances HIV-1-cell fusion and HIV-1 infection." (PMID 37106761, 2023). "Interestingly, the small amounts of viral particles produced in the presence of wt-HDAC6 and the Nef-PPAA mutant, which is unable to target HDAC6, also presented lower infection capacities (HIV-1 infection capacity/Nef-PPAA histogram)." (PMID 31736889, 2019). "A key restriction factor for HIV-1 infection that we characterized is the cytoplasmic enzyme HDAC6 (histone deacetylase 6), and more recently the transactive response of the DNA-binding protein (TARDBP or TDP-43) together with HDAC6 (i.e., the TDP-43/HDAC6 axis)." (PMID 36140273, 2022). "Therefore, it is plausible that a cellular factor that can balance cellular HDAC6 levels could regulate its anti-HIV functions and cell permissivity to HIV-1 infection." (PMID 35682862, 2022). "Furthermore, productive early HIV-1 infection requires the inhibition of autophagy and its related machinery, such as the pro-autophagic and anti-HIV-1 HDAC6 enzyme, whereas non-productive signaling in bystander target cells promotes late autophagy and subsequent cell death." (PMID 35682862, 2022).
ischemia (10 papers, 2015 to 2025). A hypoperfusion of the BLOOD through an organ or tissue caused by a PATHOLOGIC CONSTRICTION or obstruction of its BLOOD VESSELS, or an absence of BLOOD CIRCULATION. "In this study, the neuroprotective effects and the underlying mechanisms of HDAC6 inhibition were assessed in an ischemia-reperfusion injury model." (PMID 31354911, 2019). "Using HDAC6 mutant mice, we studied whether HDAC6 deficiency regulates neuronal death after ischemia." (PMID 35585040, 2022). "In ischemia, specific HDAC isoforms (e.g., HDAC1, HDAC2, HDAC3, and HDAC6) have been implicated in microglial activation, glial reactivity, and disruption of immune balance." (PMID 40867911, 2025). "Because HDAC6 modulates the myofibril stiffness and diastolic function of the heart, we propose that HDAC6 functioned as an important mediator of ischemia‐induced cardiac dysfunction in mice under our experimental conditions." (PMID 39232846, 2024). "Quantitative PCR (qPCR) also showed a time-dependent increase in Hdac6 mRNA after ischemia, suggesting increased Hdac6 transcription in the penumbra region of the cortex after ischemic stroke." (PMID 35585040, 2022). "In the present study, we observed that HDAC6 was markedly activated in kidneys subjected to ischemia- and cisplatin (cis)-induced AKI treatment." (PMID 36552715, 2022). "In the present study, we sought to address these issues by utilizing the highly selective HDAC6 inhibitor Tubastatin A (TA) and HDAC6 knockdown in a mouse model of ischemia- and cisplatin-induced AKI." (PMID 36552715, 2022). "During ischemia, HDAC6 is upregulated, promoting axonal degeneration and mitochondrial dysfunction." (PMID 40867911, 2025). "Furthermore, MIF K78 acetylation was decreased in the penumbra regions of the cortex 3 days after ischemic stroke, likely resulting from increased HDAC6 expression in the cortex after ischemia." (PMID 35585040, 2022). "HDAC6 protein was augmented in the penumbra regions 3, 5, and 7 days following ischemia." (PMID 35585040, 2022). "Other HDACs can also negatively affect cardiac functioning: overexpression of HDAC4 in mouse cardiomyocytes reduced functional recovery after ischemia/reperfusion injury, while excessive activity of HDAC6 in diabetic rats increased their vulnerability to ischemia/reperfusion injury." (PMID 34884505, 2021). "HDACs’ class II sometimes can have controversial roles: The overexpression of HDAC4 in mouse ischemia/reperfusion model resulted in reduced myocardium recovery and excessive activity of HDAC6 in diabetic rats was also related to increased vulnerability to ischemia/reperfusion injury." (PMID 32650632, 2020). "In this light, pan-inhibition of histone deacetylase (HDAC) activity is efficacious in animal models of cerebral ischemia and specific knockdown of HDAC3 or HDAC6 promotes survival of cortical neurons in an in vitro model of ischemia employing oxygen and glucose deprivation." (PMID 26541514, 2015). "Furthermore, HDAC6 was significantly overexpressed in neurons and astrocytes in the semi-dark band of the rat cerebral cortex induced by PTS, and additionally co-localized with TUNEL-positive apoptotic cells, HDAC6 may be involved in ischemia-induced apoptotic cell death." (PMID 40356977, 2025). "Although direct studies in ischemia are lacking, findings from HDAC-inhibitor-driven regulation of other T cell subsets (Tregs and Th17) imply that HDAC6 may similarly govern CD8+-mediated immune responses." (PMID 40867911, 2025).
acute kidney injury (9 papers, 2018 to 2023). Sudden and sustained deterioration of the kidney function characterized by decreased glomerular filtration rate, increased serum creatinine or oliguria. "For example, HDAC6 inhibitor attenuates renal tubular damage and reduces apoptotic cell death by suppressing oxidative stress in acute kidney injury (AKI) mice." (PMID 30046381, 2018). "Meanwhile, the elevated expression and activity of HDAC6 have confirmation of participating in various kidney diseases including acute kidney injury (AKI), polycystic kidney disease, lupus nephritis, renal cancer, and hypertensive nephropathy." (PMID 37545520, 2023). "Histone deacetylases 6 (HDAC6) has been reported to be involved in the pathogenesis of cisplatin-induced acute kidney injury (AKI)." (PMID 31894849, 2020). "Histone deacetylases 6 (HDAC6) has been reported to be involved in the pathogenesis of rhabdomyolysis-induced acute kidney injury (AKI)." (PMID 31639165, 2019). "However, the role of HDAC6 in ischemic acute kidney injury (AKI) and the mechanism by which HDAC6 inhibition protects tubular cells after AKI remain unclear." (PMID 36552715, 2022). "Histone deacetylase 6 (HDAC6) contributed to the pathogenesis of rhabdomyolysis-induced acute kidney injury (AKI) and selective inhibition of HDAC6 activity may be a promising strategy for the treatment of AKI." (PMID 29632491, 2018). "In the past decade, several highly selective HDAC6 inhibitors have been developed, Tubastatin A (TA), has been found to be effective in improving polycystic kidney disease (ADPKD), hypertensive nephropathy, acute kidney injury (AKI) and peritoneal fibrosis in animal models." (PMID 35559244, 2022).
Charcot-Marie-Tooth disease (9 papers, 2013 to 2025). An inherited degenerative disorder involving the peripheral nerves. "Cultured DRG neurons from a mutant HSPB1 mouse model of Charcot-Marie-Tooth disease showed deficits in axonal transport and this deficit was rescued by the HDAC6 inhibitors ACY-738 and ACY-775." (PMID 30935091, 2019). "Recent studies of Charcot-Marie-Tooth disease suggest that HDAC6 may be a promising target for this disorder as well." (PMID 30935091, 2019). "HDAC6 is a therapeutic target in the Charcot-Marie-Tooth disease." (PMID 31354911, 2019).
cystic fibrosis (9 papers, 2017 to 2024). Autosomal recessive disorder caused by pathogenic variants in the CFTR gene (cystic fibrosis transmembrane conductance regulator), which encodes a chloride and bicarbonate channel expressed in epithelial cells, and follow the diagnosis criteria. "The data herein obtained also complement and in part explain our previous results with selective HDAC6 inhibitors able to reduce inflammation and bacterial load in chronic infection models recapitulating the cystic fibrosis phenotype." (PMID 38371939, 2024). "Compelling new supporthas been provided for histone deacetylaseisoform 6 (HDAC6) as a common thread in the generation of the dysregulatedproinflammatory and fibrotic phenotype in cystic fibrosis." (PMID 35148101, 2022). "SAHA, HDAC6-shRNAs treatment, or Tubacin (selective HDAC6-inhibitor) could reduce neutrophil activities, thus regressing cystic fibrosis-lung disease." (PMID 34512154, 2021). "We have demonstrated a role for microtubule dysregulation in several phenotypes in cystic fibrosis, phenotypes that can be mimicked in WT cells by knock-down of TPPP expression and reversed by inhibition of HDAC6." (PMID 34046074, 2021). "The hypothesis of this study was that Hdac6 depletion would restore cystic fibrosis responses to bacterial challenge to more wild type profiles using a CF mouse model." (PMID 31311988, 2019).
diabetes (9 papers, 2015 to 2025). "Next, we evaluated HDAC6 activity, total Prdx1 levels, and acetylated-Prdx1 levels in diabetic and nondiabetic rats to explore the underlying mechanism of aggravated MI/R injury in diabetes." (PMID 30046381, 2018). "Here, we present data to show that HDAC6 levels are regulated by the lncRNA H19 in the skeletal muscle during diabetes and this regulation modulates IRS1 levels, thereby exerting effects on insulin signaling." (PMID 35842608, 2022). "The present study reveals an interesting aspect of HDAC6 regulation by the lncRNA H19 in the skeletal muscle during diabetes." (PMID 35842608, 2022). "This indicates that elevated levels of HDAC6 as seen in skeletal muscle during diabetes are possibly mediated by decreased levels of lncRNA H19." (PMID 35842608, 2022). "IHC staining demonstrated CD-1 mice had higher expression levels of HDAC6 in renal tubular cells at 4 and 12 weeks after the induction of diabetes as comparing to normal mice." (PMID 35910382, 2022). "Next, we determined the effect of the HDAC6 specific inhibitor Tubastatin A (TS), on diabetes-induced increase in HDAC6 expression and activity in the retina of diabetic rats." (PMID 32660051, 2020). "These diverse functions of HDAC6 can be used as potential therapeutic targets in various diseases, such as systemic lupus erythematosus, cancer, and diabetes." (PMID 28673326, 2017). "These diverse functions of HDAC6 offer potential therapeutic targets in various diseases such as systemic lupus erythematosus, cancer, and diabetes." (PMID 28673326, 2017). "Studies have shown that the activation of ERK1/2 in diabetic retina promotes the expression of histone deacetylases 6 (HDAC6), thereby increasing the level of apoptosis and autophagy, and these pathological changes can be mitigated by inhibiting the ERK1/2 signaling pathway." (PMID 40417223, 2025). "miR-22 can regulate the PTEN/AKT pathway and target HDAC6; miR-206 and miR-1a can suppress hepatic lipogenesis; miR-29b and miR-9 are involved in insulin sensitivity and diabetes; miR-31 and miR-32 participate in differentiation of stem cells into adipocyte and lipid metabolism in oligodendrocytes." (PMID 25675096, 2015). "This study identifies the lncRNA H19-HDAC6 axis as a significant regulator of cellular IRS1 levels and impaired levels of lncRNA H19 and HDAC6 alter IRS1 levels in the skeletal muscle during diabetes." (PMID 35842608, 2022). "To conclude, our study identifies the lncRNA H19 as a critical determiner of cellular IRS1 levels and during diabetes, decreased levels of this lncRNA promotes an inhibition in IRS1 gene expression, possibly due to increased deacetylation mediated by HDAC6 in the skeletal muscle." (PMID 35842608, 2022). "Likewise, we previously reported that pan-HDAC inhibition attenuates renal growth in early experimental diabetes; a finding that we attributed to downregulation of the epidermal growth factor receptor (EGFR), which may itself be regulated by HDAC6." (PMID 29449811, 2018). "However, whether HDAC6 affects α‐tubulin deacetylation in podocytes of patients with diabetes mellitus (DM) has not been determined." (PMID 32885602, 2020).